CHCHD1 (coiled-coil-helix-coiled-coil-helix domain containing 1)
Synonyms: MRP-S37; C10orf34; FLJ25854; mS37; C2360
Tractability: Small molecule: a structure with a bound ligand is known. PROTAC: ubiquitination databases record sites on it; its protein half-life has been measured.
Gene: Protein-coding gene on chromosome 10 (73,782,047 to 73,783,652, forward strand). Ensembl gene ENSG00000172586.
Subcellular location: Mitochondrion; Nucleus
Subcellular location (Human Protein Atlas): Mitochondria; Nucleoplasm; Cytosol; Nucleoli fibrillar center
Pathways (Reactome):
Metabolism of proteins: Mitochondrial ribosome-associated quality control; Mitochondrial translation elongation; Mitochondrial translation initiation; Mitochondrial translation termination
Gene Ontology:
Molecular function: protein binding; RNA binding
Biological process: mitochondrial translation
Cellular component: fibrillar center; mitochondrion; nucleoplasm; nucleus; mitochondrial inner membrane; mitochondrial small ribosomal subunit; mitochondrial ribosome
Genetic constraint (gnomAD): Loss-of-function variants: 11 observed, 11 expected, observed/expected ratio (o/e) 1, 90% interval 0.63 to 1.63. The upper end of that interval is the gene's LOEUF score, 1.63, which puts it in group 6 of 6, group 1 being the genes least tolerant of losing a copy. Missense variants: 138 observed, 156.9 expected, observed/expected ratio (o/e) 0.88, 90% interval 0.76 to 1.01. Synonymous variants: 56 observed, 63.69 expected, observed/expected ratio (o/e) 0.88, 90% interval 0.71 to 1.1.
Homologues: Orthologues: chimpanzee CHCHD1 (100% identical), macaque CHCHD1 (90% identical), guinea pig CHCHD1 (87% identical), rabbit CHCHD1 (86% identical), dog CHCHD1 (85% identical), rat Chchd1 (84% identical), mouse Chchd1 (83% identical), pig CHCHD1 (68% identical), tropical clawed frog chchd1 (51% identical), zebrafish chchd1 (41% identical), Drosophila melanogaster CG12848 (30% identical), Caenorhabditis elegans C24D10.6 (27% identical).
Diseases named in the same sentence as CHCHD1 in open-access papers:
CHCHD1 is named in the same sentence as 8 diseases in open-access papers, as found by Europe PMC text mining. Sharing a sentence is not in itself a finding about the gene and the disease. The quoted sentences say what the papers report.
cervix (1 paper, 2016). "We have identified and validated CHCHD1, SRSF9 and TMBIM6 as reference genes for studying hypoxia-related gene expression in fresh-frozen clinical samples from squamous cell carcinoma of the uterine cervix by RT-qPCR." (PMID 27244197, 2016).
squamous cervical cancer (1 paper, 2016). "Thus, CHCHD1, SRSF9 and TMBIM6 seem to be suitable reference genes for studying hypoxia-related gene expression in squamous cervical cancer samples by RT-qPCR." (PMID 27244197, 2016).
CHCHD1 also shares sentences with these, for which no sentence is quoted: tumor (2 papers); diabetes (1); heart failure (1); Obesity (1); osteosarcoma (1); squamous cell carcinoma (1).